RETN (resistin)
Diseases named in the same sentence as RETN in open-access papers (continued):
Sharing a sentence is not in itself a finding about the gene and the disease.
Insulin resistance (continued). "Furthermore, resistin appears to be a pivotal mediator of insulin resistance associated with inflammatory conditions." (PMID 36674646, 2023). "Periodontitis is characterized by an increase of local immune-inflammatory factors, which in turn regulate resistin mRNA levels in human PBMCs, thus indicating resistin as a possible link in the well-known association between inflammation and insulin resistance." (PMID 36829785, 2023). "In line with our findings, a previous study also unveiled that decreased MALAT1 expression caused by exercise could suppress insulin resistance in T2DM via increasing miR-382-3p expression through synchronous inhibition of resistin." (PMID 37740187, 2023). "The T allele of RETN (resistin) rs10401670 could interact with a low calorie, high fat diet and is significantly connected with insulin resistance and triglycerides." (PMID 37571378, 2023). "For obese patients, elevated adiponectin, leptin, and resistin may increase the risk of kidney cancer through their demonstrated effects on inflammation, insulin resistance, cell growth, and proliferation." (PMID 36069056, 2023). "The RESISTIN pathway enhances insulin resistance and diabetes susceptibility." (PMID 38082425, 2023). "Moreover, as hormones expressed in adipose tissue, adiponectin, leptin, and resistin were all closely associated with insulin resistance." (PMID 36277708, 2022). "Leptin and resistin are proinflammatory adipokines associated with energy homeostasis, the central control of food intake, inflammation, cardiovascular disease, and insulin resistance, while adiponectin has antidiabetic, anti-inflammatory, and antiatherogenic properties." (PMID 36500974, 2022). "Besides adiponectin, Citrus seems to act reducing other adipocytokines, as leptin and resistin, which regulate the appetite and glucose metabolism and have been associated with insulin resistance." (PMID 35237168, 2022). "However, there are many debates on the association between resistin and insulin resistance in human studies." (PMID 34996484, 2022). "In the present study, the positive effect of LDAT via PPAR and AMPK effects on insulin resistance may cause the decrease in leptin and resistin levels and the increase in adiponectin levels." (PMID 33641315, 2021). "On the other hand, adiponectin, leptin, and resistin are associated with insulin resistance." (PMID 33292449, 2020). "Finally, in differentiated murine 3T3-L1 adipocytes, the addition of pomegranate fruit extract or EA significantly suppressed resistin secretion (an adipokine associated with dyslipidemia and insulin resistance) via promoting its degradation at protein level." (PMID 33287432, 2020). "Resistin (RETN) is an adipocytokine associated with inflammation and insulin resistance." (PMID 32117953, 2020). "It was reported that the relation adiponectin/resistin index, may be a useful integrated determinant for diagnostic of insulin resistance or metabolic syndrome and appears to play a role in inflammation pathways." (PMID 32344627, 2020). "Additionally, resistance to resistin due to prolonged gut dysbiosis makes an individual susceptible to insulin resistance." (PMID 31891582, 2019). "Studies have postulated that adipokines such as adiponectin and resistin may be involved in the pathogenesis of insulin resistance and vitamin D deficiency." (PMID 31252594, 2019). "In line with this, human resistin has been primarily associated with inflammatory responses by promoting immune cell recruitment, whereas in mice it has been mostly linked to the development of type 2 diabetes and obesity-mediated insulin resistance." (PMID 31443349, 2019). "In the present population, other mechanisms that increase insulin resistance (e.g., inflammation, klotho, malnutrition, etc.)may have decreased the association between resistin and FGF23." (PMID 30228288, 2018).
Insulin resistance (continued). "Additionally, in transgenic mice, production of human resistin from macrophages was associated with increased inflammation and contributed to the acquisition of insulin resistance." (PMID 29566726, 2018). "Moreover, we did not perform multivariate adjusted analyses for the potential associations of resistin, vaspin and visfatin with atherosclerosis or insulin resistance." (PMID 29848323, 2018). "Elevated serum resistin levels are associated with insulin resistance, T2DM, and CVD." (PMID 29165404, 2017). "It is likely that resistin is linked to obesity and insulin resistance." (PMID 28596789, 2017). "Moreover, mRNA levels of genes encoding resistin, a marker of insulin resistance, and PPAR-γ were higher in mice in the FF-S group than in mice in the NC-S group (RR = 1.47, 2.20 for PPAR-γ1 and 21.94 for PPAR-γ2)." (PMID 29179698, 2017). "Model 3 shows that presence of insulin resistance was positively associated with resistin (OR = 1.017, p = 0.001), IL-6 (OR = 1.393, p = 0.002) and glycated hemoglobin (OR = 3.332, p = 0.036) and negatively associated with age (OR = 0.921, p = 0.024) and PAI-1 levels (OR = 0.981, p = 0.017)." (PMID 26862350, 2016). "Elevated levels of resistin are postulated to cause insulin resistance." (PMID 27430475, 2016). "However, debate still continues over the association of SNPs in the RETN gene with BMI, insulin resistance, markers of metabolic syndrome and T2DM." (PMID 26097512, 2015). "In addition, the adipose tissue around the heart is a metabolically active organ that secretes FFA, resistin and other adipokines, which are strongly linked with insulin resistance." (PMID 24884541, 2014). "An inflammation-associated increase in the release of resistin into circulation might contribute to the prothrombotic state observed under conditions associated with insulin resistance, including PCOS." (PMID 23721173, 2013). "MSG may cause obesity and nonfatty liver and increased mRNA level of IL-6, TNFα, resistin, and leptin in visceral fat tissue, which might all predispose insulin resistance in later life." (PMID 24455747, 2013). "Resistin is a 12-kDa polypeptide that was initially linked to insulin resistance in animal models." (PMID 23497617, 2013). "This is of importance as resistin may represent one of the mechanisms underlying the occurrence of muscle insulin resistance observed in response to central GC administration." (PMID 22479501, 2012). "Recombinant resistin caused severe hepatic insulin resistance in rodents." (PMID 22110480, 2012). "Although this supports the pathophysiological relevance of human resistin in insulin resistance, it remains controversial whether circulating resistin is associated with insulin resistance, T2DM, or adiposity in humans." (PMID 20300528, 2010). "In summary, female sex was associated with higher levels of inflammatory markers, insulin-resistance promoting adipokines (leptin and resistin), natriuretic peptides, markers of calcification and coagulation factor levels and activity, potentially contributing to higher CVD risk." (PMID 20140090, 2010). "In rodents, resistin is derived exclusively from adipocytes, circulates at increased levels in obese animals, and causes dysregulated hepatic glucose production, leading to insulin resistance." (PMID 15578112, 2004). "Indeed, induction of acute inflammation by administration of LPS causes insulin resistance in humans, and here we have demonstrated the concomitant induction of resistin." (PMID 15578112, 2004). "Indeed, a randomized clinical trial showed that CBD reduced circulating resistin, a hormone associated with insulin resistance, and increased glucose-dependent insulinotropic peptide (GIP), which plays a role in preserving pancreatic β-cell function in T2D patients." (PMID 41402937, 2025).
Insulin resistance (continued). "Additionally, Resistin levels were highly elevated (median: 46,889.39 pg/mL), supporting its role as a pro-inflammatory adipokine that may further exacerbate insulin resistance and cardiovascular risk." (PMID 40944271, 2025). "However, a high level of resistin is associated with insulin resistance and diabetes." (PMID 37108530, 2023). "The role of resistin in the development of insulin resistance associated with GDM remains unclear." (PMID 34652617, 2021). "Thus, the resistin level might be linked to the control of insulin resistance and metabolic syndrome." (PMID 32393214, 2020). "In addition, association between resistin and triglyceride levels indicates that viral hepatitis could drive insulin resistance and lipid dysregulation." (PMID 28085952, 2017). "However, further long-term and interventional studies with larger sample sizes are warranted, to give a direct cause-effect relationship between resistin and chronic periodontitis and to determine the exact molecular mechanism involved in increased insulin resistance." (PMID 24692844, 2014). "Additionally, our study suggests that inflammation-associated increase in the release of resistin into circulation might contribute to the prothrombotic state observed under conditions associated with insulin resistance, including PCOS." (PMID 23721173, 2013). "Dyslipidemia in PsA arises from multiple mechanisms, including systemic inflammation, insulin resistance, and imbalances in adipokines such as leptin, adiponectin, and resistin." (PMID 42187996, 2026). "Although leptin and adiponectin help regulate energy and metabolism, other variables such as TNF-α, IL-6, and resistin can worsen insulin resistance." (PMID 40002424, 2025). "These adipokines are intrinsically associated with insulin sensitivity: high levels of resistin and PAI-I are associated with insulin resistance, while high levels of adiponectin are associated with insulin sensitivity." (PMID 41322229, 2025). "Leptin and resistin are involved in insulin resistance; however, reduced levels of adiponectin are unable to counter these effects." (PMID 41220583, 2025). "Observational studies further reveal inconsistent correlations between resistin and insulin resistance, complicated by confounding factors including renal dysfunction and glycemic control." (PMID 41347124, 2025). "Adipokines are proinflammatory, such as TNF-α, IL-6, and resistin, which participate in inflammation and activation of other inflammatory pathways that lead to insulin resistance and metabolic diseases." (PMID 40013194, 2025). "Excess adipose tissue can elevate the expression of inflammatory cytokines (such as TNF-α) and adipokines (like leptin and resistin), both of which contribute to the pathogenesis of insulin resistance by disrupting insulin signaling and action." (PMID 40724174, 2025). "This is a contradictory result compared to previous studies, which mentioned resistin as a link between adiposity and insulin resistance." (PMID 41011232, 2025). "Considering the effects of resistin on inflammatory response and insulin resistance, it becomes important to investigate its role in obesity." (PMID 41417360, 2025). "Future studies should investigate genetic variations within this population, particularly single nucleotide polymorphisms (SNPs), which differentially influence amounts of resistin and insulin resistance between Mexican, Chinese, and European populations." (PMID 40362681, 2025). "We previously reported that resistin promotes hypothalamic inflammation and insulin resistance through the TLR4 receptor." (PMID 40759954, 2025). "The relative levels of these adipokines are such that they adversely affect insulin sensitivity; adiponectin improves insulin signaling, while resistin blocks it, thus leading to insulin resistance and facilitating the progression from MASLD to T2DM." (PMID 41220583, 2025).
Insulin resistance (continued). "The current study data showed improvement in the gene expression of adiponectin and resistin in visceral adipose tissue that reveals the effective action on insulin resistance of NA/STZ-induced diabetic rats." (PMID 40430475, 2025). "Excess visceral fat can secrete higher levels of hormones such as leptin and resistin, disrupting insulin signaling, aggravating insulin resistance, and impairing cholesterol metabolism and gallbladder function." (PMID 41287115, 2025). "Resistin is connected with insulin resistance and inflammation, whereas visfatin is connected to fibrosis progression in MASLD." (PMID 41220583, 2025). "Resistin was a significant predictor of insulin resistance, with an OR of 2.85 (CI: 1.57–5.98, p = 0.002), meaning that each unit increase in resistin nearly triples the odds of insulin resistance." (PMID 40077669, 2025). "It was reported that resistin is involved in the pathogens of inflammation, insulin resistance, atherosclerosis, and atherogenic dyslipidemia." (PMID 39962072, 2025). "The level of WAT-derived resistin is increased in obese mice and is strongly related to insulin resistance." (PMID 40179260, 2025). "In humans, resistin is primarily expressed in the monocytes and macrophages, where it contributes to the development of insulin resistance." (PMID 40428823, 2025). "Conversely, adipocytokines TNFα and resistin, which have been shown to contribute to insulin resistance, had their mRNA levels downregulated by repeated palmitoleic acid delivery." (PMID 39940428, 2025). "Compared with adiponectin and apelin, described as beneficial adipokines, others, resistin and visfatin, are more deleterious in the context of insulin resistance, while leptin has a more controversial effect." (PMID 40943107, 2025). "It has been reported that proinflammatory adipokines (resistin) promote insulin resistance and influence liver function to increase hepatic glucose and TG production." (PMID 40385742, 2025). "Resistin is a polypeptide that is crucial for numerous biological processes, including lipid metabolism, inflammation, and insulin resistance, as studied in rodent models." (PMID 40216734, 2025). "In patients with excess body weight, it was 1266 pg/mL, and obese patients with insulin resistance had an average resistin level of 1331 pg/mL." (PMID 39796247, 2025). "Increased M1 macrophages secrete pro-inflammatory mediators such as TNF-α, IL-1β and resistin, which act on adipocytes to induce a state of insulin resistance, leading to a positive feedback loop of inflammation and insulin resistance." (PMID 40084146, 2025). "Complementing this, mechanistic work in 2024 revealed 2-AG-induced CB1 signalling in monocytes upregulates resistin, sparking adipose inflammation and systemic insulin resistance, reversed by CB1 blockade." (PMID 40806101, 2025). "Studies have demonstrated that serum resistin levels are higher in patients with insulin resistance compared to healthy individuals, with an even more pronounced increase in those diagnosed with T2D." (PMID 40283140, 2025). "Numerous studies indicate that increased resistin levels are positively correlated with the development of insulin resistance, diabetes and cardiovascular diseases such as dyslipidemia, atherosclerosis and hypertension." (PMID 40491594, 2025). "While sdLDL is highly atherogenic due to its small size, increased artery wall penetration, and oxidative vulnerability, resistin plays a role in insulin resistance and systemic inflammation." (PMID 41315571, 2025). "From the perspective of evaluating insulin resistance through the determination of serum resistin levels, bilateral CIMT demonstrated a positive correlation with elevated serum resistin concentrations." (PMID 40077669, 2025). "Chronic inflammation in adipose tissue releases pro-inflammatory adipokines, such as resistin and leptin, which exacerbate insulin resistance." (PMID 41007787, 2025).
Insulin resistance (continued). "Although many studies have shown a central role for resistin in regulating food consumption, energy homeostasis, and hepatic insulin resistance, a few studies have focused on the central cardiovascular function and its treatment sites." (PMID 38164476, 2024). "There is also research indicating that ERS in adipocytes of obese mice can downregulate the expression of resistin in cultured mouse adipocytes, linking obesity and insulin resistance through adipose tissue." (PMID 38638434, 2024). "Adiponectin enhances insulin sensitivity, whereas resistin and pro-inflammatory cytokines (e.g., TNF-α) are associated with insulin resistance." (PMID 39683486, 2024). "A strong correlation between serum resistin levels and insulin resistance has been observed in rodent studies; however, the correlation between serum resistin levels and insulin resistance in human studies is controversial." (PMID 38238841, 2024). "In the murine models, resistin is thought to impair glucose homeostasis, leading to glucose intolerance and insulin resistance." (PMID 39190724, 2024). "Significantly higher levels of resistin and the Homeostasis Model Assessment of Insulin Resistance Index (HOMA-IR) were found in CRC patients compared with healthy subjects." (PMID 39184804, 2024). "In both mouse models, a high-fat diet increased the accumulation of endocannabinoid ligands in adipose tissue, which recruited the CB1R-positive cells that secrete resistin, leading to adipose tissue inflammation and insulin resistance." (PMID 39050819, 2024). "It was first identified in mice in 2001 as a signal molecule produced by adipocytes, and named resistin because it was thought to be involved in the development of insulin resistance." (PMID 38218787, 2024). "Most studies investigating the relationship between resistin and insulin resistance propose that resistin is positively correlated with insulin resistance by inhibiting the IRS-1/PI3K/AKT pathway." (PMID 40302954, 2024). "Based on the role of resistin in inflammation, a link has been proposed between resistin and insulin resistance, although overall data is inconclusive." (PMID 39525621, 2024). "Resistin was initially identified for its role in promoting insulin resistance which controlled by the RETN gene in humans." (PMID 39538244, 2024). "Therefore, the association between resistin and insulin resistance remains unclear in humans." (PMID 39050819, 2024). "OAGB was superior in the control of T2DM, which was in parallel with weight loss, fasting resistin levels, and HOMA-IR changes, suggesting a possible effect of resistin on glucose metabolism and insulin resistance." (PMID 38833355, 2024). "For example, resistin and adiponectin have differing impacts on inflammation and insulin resistance, but both are crucial in the progression of disorders like MetS and T2DM." (PMID 39596980, 2024). "The decreases at 1 year were in correlated with weight loss, BMI change, HbA1C, and HOMA-IR in both groups, suggesting a possible effect of resistin on glucose metabolism and insulin resistance." (PMID 38833355, 2024). "Initially identified as an adipocytokine hormone in adipose tissue, it was named "resistin" due to its role in inducing insulin resistance in obese mice." (PMID 38562275, 2024). "Although human resistin is primarily produced by macrophages rather than adipocytes, experimental studies indicate that human resistin exacerbates adipose tissue inflammation and leads to insulin resistance." (PMID 38638434, 2024). "We confirmed that circulating CB1R-postive cells secrete resistin and infiltrate into the target tissues such as visceral adipose tissue having high level of 2-AG, leading to inflammation and insulin resistance." (PMID 39050819, 2024). "While initially recognized as an adipocyte-secreted factor involved in insulin resistance, resistin is predominantly expressed in monocytes, macrophages, spleen, bone marrow-derived cells, and adipose cells, albeit at low levels." (PMID 38486190, 2024).